GSDME (gasdermin E)
Diseases named in the same sentence as GSDME in open-access papers (continued):
Sharing a sentence is not in itself a finding about the gene and the disease.
infection (continued). "With GSDME playing a crucial role in dictating cell death modes, strategic targeting of this protein opens avenues for modulating inflammatory responses during infection and inflammation, presenting potential therapeutic implications." (PMID 38195694, 2024). "Infection with intact virus weakly triggered generation of the GSDMD-N form what stays in line with the recent finding that gasdermin E is the primary pyroptosis executor in lung epithelial cells." (PMID 38664396, 2024). "Similar to what was observed in SH‐SY5Y cells, the NPCs did not express GSDMD but induced significant cleavage of CASP3, PARP, and GSDME following infection, and this led to necrotic cell death." (PMID 37646198, 2023). "In the current study, we characterized the relative contributions of T3SS, the NLRP3 versus the NLRC4 inflammasomes, and GSDMD and GSDME to IL-1β release and pyroptosis in neutrophils versus macrophages following infection with P. aeruginosa." (PMID 37730693, 2023). "In the hfOBSC system, we observed more pronounced infection with HSV‐2 than HSV‐1, which was associated with cleavage of CASP3, PARP, and GSDME." (PMID 37646198, 2023). "Overexpression of CPA4 in HLCZ01 cells via a lentiviral infection system was found to inhibit HGS-ETR1/2-induced GSDME cleavage, and the number of pyroptotic cells decreased, LDH release and the number of PI-positive cells decreased." (PMID 38049405, 2023). "Since EIB202 is an intracellular bacterium, we thought that the Caspase-GSDME signaling should be activated by the infection of intracellular bacteria or the recognition of intracellular LPS." (PMID 37134086, 2023). "GSDME can compensate for the inactivation of GSDMD upon infection with coronavirus in epithelial cells or enterovirus 71 in Hela cells and induce pyroptosis." (PMID 37771587, 2023). "In this study, we observed activation of GSDME, as well as multiple CASPs, in turbot Scophthalmus maximus during the infection of the bacterial pathogen Vibrio harveyi." (PMID 35610210, 2022). "At 24 hr post-infection, caspase-3 underwent activation and obvious cleavage of GSDME was shown in infected JEG-3 cells." (PMID 35972780, 2022). "The abundance of GSDME, the replication and infection levels of ZIKV in cells, and the ZIKV-induced LDH release were quantified." (PMID 35972780, 2022). "GSDME-mediated pyroptosis is also observed in enterovirus A71 (EV71) infection of HeLa and SK-N-SH cells." (PMID 35806033, 2022). "Cleaved GSDME was readily detected in cell lysates from 12 h post-Brazil/78 infection." (PMID 40481027, 2025). "However, dual silencing of GSDMD and GSDME was required to reduce IL-1β secretion following Brazil/78 infection." (PMID 40481027, 2025). "Here, GSDME deficiency modestly reduced levels of IL-1β but not IL-18 in the airways following HKx31 infection, potentially due to differential regulation of the expression of these cytokines in vivo." (PMID 40481027, 2025). "In addition to this, evidence points to a predominant caspase-3/GSDME activation during infection with HCoV-229E, as well as with other coronaviruses and RNA viruses." (PMID 38932190, 2024). "Nonetheless, our findings suggest that both GSDMB and GSDME may play a role in pyroptosis of canine EICs induced by PSCs infection." (PMID 39679172, 2024). "We also examined the role of GSDMD and GSDME during infection." (PMID 37730693, 2023). "On the other hand, PGE2 and GSDME promote inflammation in response to IV infection." (PMID 37773712, 2023). "Indeed, in HeLa, HBMEC and NSC34 cells we found that GSDME was cleaved to produce the N-terminal fragment only after infection." (PMID 35765029, 2022). "Zika virus (ZIKV) infection activates gasdermin E (GSDME) via extrinsic apoptotic pathway." (PMID 35972780, 2022). "We next determined whether the pyroptosis executors, GSDMD and GSDME, were activated during the infection of JEG-3 cells with ZIKV." (PMID 35972780, 2022).
infection (continued). "We found that, 24 h after AH/1 infection, the PI positive-stained populations of A549-vector control cells and A549-GSDME/− cells were 56.3% and 9.7%, respectively, and that the PI positive-stained populations of Raw-vector control cells and Raw-GSDME/+ cells were 26.4% and 67.5%, respectively." (PMID 35087672, 2022). "Interestingly, we observed cleaved GSDME in endothelial cells at day 3 post-infection, suggesting that GSDME could potentially promote endothelial damage and vascular leak of cytokines and other factors into the blood." (PMID 40481027, 2025). "The same study shows that infection with herpes simplex virus 1 causes GSDME activation when the virus lacked the protein ICP27, suggesting that ICP27 inhibits GSDME-driven pyroptosis by a still-unknown mechanism." (PMID 35455985, 2022). "We found that RSV-induced plasma membrane rupture and IL-1β release were unaffected by GSDMD knockout, but abolished upon GSDME deletion, indicating that RSV promotes GSDME-dependent pyroptosis for IL-1β secretion in late infection." (PMID 41576161, 2026). "Lastly, targeting of GSDME alone, or in combination with GSDMD, significantly limited infectious virus release at 24 h following both Brazil/78 and HKx31 infection." (PMID 40481027, 2025). "Infection of human bronchial epithelial cells revealed that IAV induces GSDME cleavage and activation, with the magnitude and kinetics of GSDME activation differing between IAV strains." (PMID 40481027, 2025). "However, if 2B* is acting to induce caspase-3-dependent (GSDME-mediated) pyroptosis (which WT EMCV is known to cause), then 2B*KO EMCV-infected cells would have less cleaved caspase-3 than WT EMCV-infected cells, at timepoints where lysis is reduced in 2B*KO EMCV infection." (PMID 39928567, 2025). "Upon infection with Yersinia, RIPK1 promotes caspase-3–dependent GSDME activation, leading to neutrophil pyroptosis." (PMID 38195694, 2024). "At the same early time of 12 h post-infection, the RIPK3 KO BMDMs started to diverge from the ZBP1 KO cells and began to show the activation of caspases and GSDMD and GSDME." (PMID 38005819, 2023). "Using immunoblotting-based biochemical analyses, we observed IAV-induced PANoptosis in BMDMs at both 12 and 24 h post-infection, as indicated by activation of CASP1, gasdermin D (GSDMD) and GSDME, along with CASP8, CASP3, and CASP7, as well as MLKL." (PMID 38005819, 2023). "During infection by influenza H7N9 virus, it activates pyroptosis mediated by gasdermin E (GSDME) in host lung alveolar epithelial cells." (PMID 35806033, 2022). "At 24 hr post infection, LDH levels in supernatant, cell viability (n=3) (G) and cleavage of GSDME, caspase-1, caspase-3, and caspase-8 were measured in ZIKV-infected JEG-3 cells." (PMID 35972780, 2022). "At 24 hr post-infection, the ZIKV-induced LDH release and GSDME activation were found to be enhanced in a virus dose-dependent manner, which implicit that the productive infection is critical to its pathogenesis." (PMID 35972780, 2022). "After infection with EV71, caspase-3 was shown to be activated and cleavage of GSDME at the amino acid pair of D270–E271 was noted." (PMID 35806033, 2022). "Moreover, at the later stages of infection, RSV induced caspase-9–mediated intrinsic apoptosis and GSDME-dependent secondary pyroptosis, thereby exacerbating cell death." (PMID 41576161, 2026). "In contrast, the response following HKx31 infection was delayed, with cleaved GSDME not detected until 24 h." (PMID 40481027, 2025). "Furthermore, certain conditions of viral, such as SARS-CoV-2, human coronavirus 229E (HCoV-229E), and enterovirus 71 (EV71) infection, have been observed to induce both GSDMD- and GSDME-mediated pyroptosis." (PMID 40503916, 2025).
infection (continued). "Further analysis revealed a slight increase in p-MLKL and the presence of mildly cleaved Gasdermin D (GSDMD) at a high MOI (multiplicity of infection), although these changes were not significant, and no cleaved form of Gasdermin E (GSDME) was observed." (PMID 40891826, 2025). "When GSDMD was suppressed, GSDME cleavage and activation remained largely constant following Brazil/78 and HKx31 infection compared to the non-targeting (NT) control." (PMID 40481027, 2025). "Histological analysis of H&E-stained murine lung tissue sections revealed that the absence of GSDME significantly limits peribronchial inflammation and epithelial damage at day 3 post-infection." (PMID 40481027, 2025). "To investigate whether 2B* was required for efficient execution of this pathway during EMCV infection, we infected HEK293T cells, which had been transiently transfected with a tagged GSDME construct." (PMID 39928567, 2025). "Notably, the intensity of GSDME, GSDMD, caspase-3, and caspase-1 cleavage was strikingly more pronounced over the time course of Brazil/78 infection, correlating with significantly greater IL-1β and LDH release at 18 and 24 h post-infection." (PMID 40481027, 2025). "GSDMD activation succeeded GSDME activation, with the p30 subunit of GSDMD, as well as caspase-1 cleavage, observed in the cell supernatants from 18 h or 36 h following Brazil/78 and HKx31 infection." (PMID 40481027, 2025). "Similarly, LDH release was only significantly compromised following HKx31 infection when both GSDMD and GSDME were suppressed." (PMID 40481027, 2025). "In accordance with the LPS-induced lung injury model, the deletion of GSDME in neutrophils did not affect the initial neutrophil recruitment at 8 h post-infection." (PMID 38195694, 2024). "Gasdermin E (GSDME), also known as DFNA5 (Deafness, Autosomal Dominant5), is a protein that is involved in programmed cell death, specificallypyroptosis, a form of cell death in response to infection or cellularstress." (PMID 38787632, 2024). "Interestingly, infection of human keratinocytes with viruses, such as VSV or HSV-1, induces GSDME-dependent pyroptosis activated by caspase-3 and release of the alarmin IL-1α." (PMID 37771587, 2023). "Conversely, induction of ER stress independent of infection through treatment with TG induced GSDME cleavage and necrosis in SH‐SY5Y cells." (PMID 37646198, 2023). "tBID started to accumulate at 16 h post‐infection with HSV‐2, which correlated with GSDME cleavage." (PMID 37646198, 2023). "Overall, these observations clearly demonstrate using genetic and pharmacological approaches that neither GSDMD nor GSDME are required for NETosis induced by PMA or following infection with T3SS expressing P. aeruginosa." (PMID 37730693, 2023). "Moreover, infection with HSV1, a DNA virus known to activate cGAS, could also trigger GSDME-mediated pyroptosis in the presence of lactic acid or HCl." (PMID 40663398, 2025). "However, different from GSDMD, GSDME knockout did not have a significant impact on PDCoV multiplication at all tested time points (12, 18, and 24 h post-infection)." (PMID 40503916, 2025). "According to the authors, the GSDME-mediated pyroptosis may not be induced in infections with other IAV strains." (PMID 40431705, 2025). "It was thus evident that infection with H7N9 could activate and switch the cell death from caspase-3-mediated apoptosis to pyroptosis in alveolar epithelial cells expressing high levels of GSDME." (PMID 35806033, 2022). "Moreover, GSDME was not cleaved into the active N-terminal fragment either in HeLa cells or GSDME-highly expressing NCI-H226 cells upon E. piscicida strains infection while it was cleaved after treatment with the caspase 3 activator staurosporine." (PMID 35186798, 2022).
infection (continued). "Thus, it has been recently described that GSDME, a protein related with pyroptosis and IL-1β release, is activated in neutrophils in a RIPK1-dependent manner and that the FADD-RIPK1-caspase 8 complex is recruited after infection to cleavage GSDMD and initiates the inflammatory cell death." (PMID 35716229, 2022). "Taking together, the results demonstrate that PToV 3CLP, driven by rVSV infection, induces a potent and specific GSDMD-mediated pyroptosis that is independent of the VSV-triggered and GSDME-mediated cell pyroptosis in IPEC-J2 cells." (PMID 41400836, 2026). "In contrast, at the peak of LDH release observed upon Brazil/78 infection, GSDMD, GSDME, or GSDMD/E suppression failed to impact cell lysis, suggesting a further mechanism exists to compromise membrane integrity." (PMID 40481027, 2025). "As infection progressed, we could observe a slight decrease in band intensity for FL GSDMD and GSDME in whole cell lysates (WCL), but not a clear appearance of GSDMD and GSDME cleaved products." (PMID 38932190, 2024). "Interestingly, while suppression of gasdermin expression did not affect virus titers at 24 h post infection, viral titers were higher at 48 hpi in NHBE cells silenced for GSDMD or GSDME compared to cells treated with control siRNA." (PMID 37680489, 2023).
bacterial infection (7 papers, 2022 to 2024). "Up-regulated IL-6 caused by bacterial infection inhibited GSDMD/GSDME-mediated pyroptosis by suppressing caspase-1/3 activation and thus play partly protective role in bacterial infection." (PMID 38022612, 2023). "The functional study of teleost GSDME is limited to turbot and common carp Cyprinus carpio, with turbot GSDMEa and common carp GSDMEb being involved in the response to bacterial infection." (PMID 39219679, 2024). "Here, we extend the study of GSDME by examining the role of GSDMEa in bacterial infection using pufferfish as a model." (PMID 39219679, 2024). "To connect bacterial infection and GSDME activation in the amphioxus, we generated a polyclonal antibody using the His-tagged BbGSDME protein expressed in BL21 as an antigen." (PMID 37134086, 2023). "To date, the regulation and function of teleost GSDME in response to bacterial infection remain elusive." (PMID 35610210, 2022). "Together, these results revealed a previously unrecognized bi-directional regulation mode of GSDME-mediated pyroptosis, and a functional difference between teleost GSDMEa and GSDMEb in the immune defense against bacterial infection." (PMID 35610210, 2022). "The findings also increase our understanding of how GSDMD versus GSDME cleavage is differentially utilized for IL-1β secretion and regulated cell death responses in neutrophils compared with macrophages, and in bacterial infections where neutrophils are the predominant cell type." (PMID 37730693, 2023). "For instance, GSDMA or GSDME might contribute to C. rodentium host defense, as both of these Gasdermins were shown to be activated and to contribute to cell death upon other bacterial infections." (PMID 37080966, 2023). "GSDME is the only direct executor of caspase-dependent pyroptosis in both canonical and non-canonical inflammasomes known to date in fish, and plays an important role in anti-bacterial infection and inflammatory response." (PMID 36685536, 2022).
kidney diseases (6 papers, 2021 to 2025). "We further employed GSDME-deficient mice to establish the experimental AKI model to verify the role of GSDME in cisplatin-induced kidney disease." (PMID 33542198, 2021). "Recent studies on the GSDMs family suggested that both GSDMD and GSDME were the executive proteins of pyroptosis, which played an important role in the development of renal diseases." (PMID 38388468, 2024). "At present, some studies have found the promoting role of GSDME in renal disease and examined the molecular mechanism of pyroptosis, including nephrotoxicity induced by chemotherapy, obstructive renal disease and acute renal injury." (PMID 37169767, 2023). "Many studies have investigated the impact of GSDME-mediated pyroptosis in kidney diseases, and these studies used multiple interventions, in vitro models, and in vivo models." (PMID 34867412, 2021). "Many studies have examined the effect of GSDME-mediated pyroptosis in kidney diseases, and these studies used multiple interventions, in vitro models, and in vivo models." (PMID 34867412, 2021). "Thus, an increasing number of kidney diseases have been suggested to be related to GSDME and its dependent pyroptosis." (PMID 35462927, 2022). "However, little is known about the role of GSDME in kidney disease, especially in DN." (PMID 37169767, 2023).
cardiovascular diseases (3 papers, 2025). "In this review, we introduce the structure and biological functions of GSDME, provide a brief overview of research strategies and experimental systems, and discuss recent scientific advances regarding GSDME in cardiovascular diseases." (PMID 41550939, 2025). "In conclusion, GSDME has emerged as a crucial mediator linking regulated cell death to inflammation in the cardiovascular diseases." (PMID 41550939, 2025). "In the context of cardiovascular diseases, studies have shown that the expression of GSDME in macrophages within atherosclerotic plaques is significantly greater than that in normal vascular tissue and that the levels of activated N-GSDME fragments are notably elevated." (PMID 41550939, 2025). "Although gasdermin E (GSDME) has been linked to the development of several cardiovascular diseases, the role of GSDME in DIC has not been thoroughly investigated." (PMID 41208882, 2025).
kidney (3 papers, 2020 to 2022). "GSDME deficiency attenuates acute kidney injury by inhibiting pyroptosis and inflammation." (PMID 35228524, 2022). "Loss of GSDME promoted the resistance to cisplatin in lung cancers." (PMID 32341339, 2020).
neurodegenerative disease (3 papers, 2021 to 2024). A disorder of the central nervous system characterized by gradual and progressive loss of neural tissue and neurologic function. "Recent studies have shown that higher levels of GSDME play a significant role in the progression of neurodegenerative diseases by translocating into neuronal mitochondria to cause mitochondrial depolarization and neuronal damage." (PMID 38172670, 2024). "Interestingly, pyroptosis, an inflammasome-associated regulatory necrosis, is closely associated with the pathogenesis of neurodegenerative diseases and METH induces ER stress that mediates GSDME-dependent pyroptosis in hippocampal neuronal cells." (PMID 34349659, 2021).
adenocarcinoma (2 papers, 2019 to 2020). A common cancer characterized by the presence of malignant glandular cells. "Therefore, we hypothesized that GSDME was a tumor suppressor gene and by knocking out this gene in mice we expected more affected GSDME KO mice and more adenocarcinomas in the GSDME KO compared to the WT mice." (PMID 31434357, 2019).
inflammation (2 papers, 2020 to 2023). Aberrant reaction of the microcirculation characterized by movement of fluid and leukocytes from the blood into extravascular tissues. "This intensified inflammatory response served to neutralize the inhibitory effects of GSDME deficiency on vascular inflammation in ApoE−/− mice." (PMID 37761020, 2023).
peripheral neuropathies (1 paper, 2026). "Intriguingly, while caspase‐1 triggers GSDMD‐mediated pyroptosis in various peripheral neuropathies, caspase‐1 instead activates gasdermin A (GSDMA) or gasdermin E (GSDME) in the CNS disorders." (PMID 41574659, 2026).
retinopathies (1 paper, 2025). "In conclusion, GSDME-mediated photoreceptor ferroptosis is crucial for inducing structural and functional damage of the retina in retinopathies caused by atRAL accumulation, thereby providing new therapeutic insights for the prevention and treatment of STGD1 and dry AMD." (PMID 41281747, 2025).